IL7R (interleukin 7 receptor)
Diseases named in the same sentence as IL7R in open-access papers (continued):
Sharing a sentence is not in itself a finding about the gene and the disease.
eczema (2 papers, 2025). "The T:T genotype shows greater IL‐7R mRNA expression, but in the context of dog exposure, the risk effect is overshadowed by an increase in cytokines and chemokines in the IL‐10 pathway that suppress eczema to a greater extent in T:T than C:C individuals." (PMID 40462597, 2025).
HCMV infection (2 papers, 2017 to 2024). "Interesting data on protection from HCMV infection arose from the analysis of the T cell response in the two cellular compartments identified according to IL-7R expression." (PMID 29112951, 2017).
head and neck cancer (2 papers, 2023 to 2025). A primary or metastatic malignant neoplasm affecting the head and neck. "IL7R+ CD8 T cells have been shown to be a stem-like tumor-reactive CD8 T cell population as was shown in head and neck cancer and is related to a better clinical outcome upon immunotherapy." (PMID 41438752, 2025).
ischemic stroke (2 papers, 2020 to 2022). A stroke disorder caused by obstruction of blood flow to the brain, due to thrombotic (local blood clot formation) or embolic (due to a blood clot or other material traveling from another site) event. "In the present study, we investigated the immune related gene expression modules, in which the SLAMF1, IL7R and NCF4 may be novel therapeutic targets to promote functional and histological recovery after ischemic stroke." (PMID 32746852, 2020).
Lymphadenopathy (2 papers, 2011 to 2022). Enlargement (swelling) of a lymph node. "Furthermore, analysis of MRL-Faslpr mice with various degrees of lymphadenopathy indicated that FRCs accumulated proportionally to the number of total LN cells, whereas IL-7Rα+ T cells accumulated at much slower rate." (PMID 22102903, 2011). "The origin of this homeostasis disturbance could be attributed to self and commensal antigen-induced lymphadenopathy, resulting in expansion of IL-7-producing FRCs and down-regulation of IL-7R in chronically activated T cells." (PMID 22102903, 2011).
lymphoproliferative disorders (2 papers, 2019 to 2024). "Correspondingly, IL7R−/− mice do not respond to IL7 and have severely reduced B- and T-cell counts; whereas, transgenic IL7-overexpressing mice develop lymphoproliferative disorders of B- and T-cell compartments." (PMID 29977016, 2019).
metastatic disease (2 papers, 2014 to 2017). "IL7R is highly expressed in T-cells and thus may be associated with infiltrating T-cells, whose presence is higher in many of the metastatic tumors in our study as indicated by higher expression of other T-cell markers such as CD3 (data not shown)." (PMID 24732363, 2014). "Nevertheless, there is a growing body of evidence linking IL-7/IL-7R signaling with tumor aggressiveness, metastatic disease, and unfavorable prognosis." (PMID 27866242, 2017).
myeloid leukemia (2 papers, 2015 to 2016). A clonal proliferation of myeloid cells and their precursors in the bone marrow, peripheral blood, and spleen. "Due to the restricted expression pattern of IL7R, IL7R mutations are limited to lymphoid malignancies, while JAK1 and JAK3 mutations could also be expected in myeloid leukemias and even in any type of cancer." (PMID 26208852, 2015).
nasal polyp (2 papers, 2022 to 2024). "To confirm the presence of IL7R-low ILC2s in vivo, we performed further analysis of nasal polyp samples by flow cytometry." (PMID 38889332, 2024). "Consequently, IL7R-low ILC2s, which are enriched in cytokine and effector mRNA expression, were notably present in nasal polyp tissue and AD lesions." (PMID 38889332, 2024). "IL-7R is expressed on naive as well as memory T cells, therefore, it can be presumed that active local adaptive immune responses are taking place in the tissue of nasal polyps that are somewhat facilitated by or due to the IL-6 expression." (PMID 36285981, 2022).
osteosarcoma (2 papers, 2020 to 2023). A usually aggressive malignant bone-forming mesenchymal neoplasm, predominantly affecting adolescents and young adults. "To validate these findings, we checked MEK6, EphA2, and IL7R also at protein level in all seven osteosarcoma cell lines after 24 h of treatment with pazopanib (10 μM), trametinib (25 nM), and their combination." (PMID 32531992, 2020). "Pazopanib + trametinib demonstrated synergistic antitumor effects in osteosarcoma models through ERK and Akt inhibition and EphA2 and IL-7R down-modulation." (PMID 32531992, 2020). "Moreover, deeply investigating the molecular perturbation evoked by pazopanib and trametinib combination, we identified EphA2, IL-7R, and MEK6 as potential novel targets in osteosarcoma." (PMID 32531992, 2020).
pulmonary hypertension (2 papers, 2021 to 2022). Increased pressure within the pulmonary circulation due to lung or heart disorder. "One study has demonstrated downregulated IL-7R expression on CD4 T cells in scleroderma patients with pulmonary hypertension, which is consistent with our results." (PMID 35663995, 2022).
septic shock (2 papers, 2018 to 2019). Shock caused by infection; frequently caused by gram negative bacteria, although some cases have been caused by other bacteria, viruses, fungi, and protozoa; characterized by fever, chills, tachycardia, tachypnea, and hypotension. "Soluble IL-7R (sIL-7R or sCD127) levels are higher in non-surviving septic shock patients." (PMID 29977234, 2018).
synovitis (2 papers, 2014 to 2016). Inflammation of a synovial membrane. "The co-localization of USPIO-P258 with IL-7Rα-expressing cells in CIA synovitis demonstrates its specific binding to the targeted receptor." (PMID 27729062, 2016).
Thrombocytopenia (2 papers, 2019 to 2020). A reduction in the number of circulating thrombocytes. "Here, we reported an atypical and delayed onset of IL7Rα-SCID in a 15-month-old girl presenting with thrombocytopenia." (PMID 31736942, 2019).
vitiligo (2 papers, 2019 to 2021). Generalized well circumscribed patches of leukoderma that are generally distributed over symmetric body locations and is due to autoimmune destruction of melanocytes. "We have also detected presence of Tbet + CD161+ ILC1 in vitiligo skin which were confirmed to be negative for CD3 and CD56 and positive for IL-7Rα CD127." (PMID 31097717, 2019).
acute respiratory distress syndrome (1 paper, 2018). Progressive and life-threatening pulmonary distress in the absence of an underlying pulmonary condition, usually following major trauma or surgery. "Lnc-IL7R has been found to participate in multiple sclerosis, chemotherapy, and acute respiratory distress syndrome (ARDS)." (PMID 29720427, 2018).
adenoma (1 paper, 2024). A neoplasm arising from the epithelium. "A higher portion of TRM found in carcinoma tissue is IL7R+, while it is mainly IL7R− TRM in normal and adenoma tissue." (PMID 39454432, 2024).
adrenal tumor (1 paper, 2021). "Our results indicated the heterogeneity of the immune system between different samples, and CD4+ T cells with the high expression level of IL-7R might be related to adrenal tumor progression, apoptosis, or factors influencing progression such as immune activation." (PMID 34905486, 2021).
allergic rhinitis (1 paper, 2022). Inflammation of the nasal mucous membranes caused by an IgE-mediated response to external allergens. "After using an IL-9 neutralizing antibody, the mRNA expression of TSLP, TSLPR, OX40, OX40L, and IL-7R decreased significantly compared with the allergic rhinitis group." (PMID 36172190, 2022). "After using an IL-9 neutralizing antibody, the mRNA expression of TSLP, TSLPR, OX40, OX40L, and IL-7R decreased significantly compared with the allergic rhinitis group, and the difference was statistically significant." (PMID 36172190, 2022). "The relative mRNA expressions of TSLP, TSLPR, OX40, OX40L, and IL-7R in the nasal mucosa of allergic rhinitis mice were considerably higher than those in the control group." (PMID 36172190, 2022). "Firstly, we detected the relative mRNA expression of TSLP, TSLPR, OX40, OX40L, and IL-7R in the nasal and sinus mucosa of allergic rhinitis mice by real-time PCR." (PMID 36172190, 2022). "The relative expressions of TSLP, TSLPR, and IL-7R in the nasal mucosa of allergic rhinitis mice were significantly higher than those in the control group." (PMID 36172190, 2022).
alopecia areata (1 paper, 2023). Loss of scalp and body hair involving microscopically inflammatory patchy areas. "In a mouse model of alopecia areata, blockade of IL-7 signaling with anti-mouse IL-7Rα antibody suppressed inflammatory responses and reversed alopecia areata." (PMID 37881433, 2023).
anaphylaxis (1 paper, 2012). An acute hypersensitivity reaction that occurs from exposure to an allergen. "Intriguingly, despite the reduced susceptibility to PIA, both IL7R−/− and L-sel−/− mice exhibited normal susceptibility to passive systemic anaphylaxis." (PMID 22935073, 2012). "In our study, we provide the first analysis of four immune molecules (IL7Rα, L-selectin, CD34, CD103) in the PIA model, to determine the effect of altered adaptive responses and cell migration on food-induced anaphylaxis." (PMID 22935073, 2012).
aortitis (1 paper, 2025). Inflammation of the aorta. "Interestingly, the mRNA expression of IL‐7R was increased in the transcriptomic analysis of LV‐GCA aortitis, and a recent study reported that IL‐7R expressing T cells are involved in the persistence of vasculitic lesions in a mouse chimeric model." (PMID 39817309, 2025).
ataxia telangiectasia (1 paper, 2014). Ataxia-telangiectasia is the association of severe combined immunodeficiency (affecting mainly the humoral immune response) with progressive cerebellar ataxia. "Levels of alpha-1-fetoprotein in serum as a potential indication for ataxia telangiectasia as well as flow cytometric analysis of IL-7Rα, IL-2Rγ, CD3 und CD45 expression in peripheral blood leukocytes showed normal results." (PMID 25205547, 2014).
Atrophy (1 paper, 2025). Any weakening or degeneration, especially through lack of use. "In addition to these effects, APOE-ε4 decreases plasma interleukin 7 (IL-7) levels and interleukin 7 receptor (IL-7R) signaling in in peripheral blood mononuclear cells, disrupting immune balance and enriching T cells, which may exacerbate neuroinflammation, hippocampal atrophy, and neuronal damage." (PMID 39858858, 2025).
autoimmune encephalitis (1 paper, 2018). Inflammation of the brain secondary to an immune response triggered by the body itself. "Similarly, in a previous report, another anti-IL-7Rα mAb prevented in vitro and ex vivo IL-7-induced pSTAT5 in primates but did not protect from brain inflammation in an experimental autoimmune encephalitis (EAE) marmoset model." (PMID 30367166, 2018).
autoimmune uveitis (1 paper, 2016). An autoimmune form of uveitis (disease). "In addition, OX40 activating antibody prolonged and exacerbated disease in a model of experimental autoimmune uveitis by upregulating IL-7Rα expression in the activated T-cell population." (PMID 27872495, 2016).
Cachexia (1 paper, 2022). Severe weight loss, wasting of muscle, loss of appetite, and general debility related to a chronic disease. "In addition, consistent with higher percentage of effector-memory CD8+ T cells in non-cachexia patients, genes relevant to the dysfunctional phenotype and the state of inactivation such as MT1X, MT1E, IL7R, and ZFP36L2 were highly expressed in CD8+ T cells in non-cachexia patients." (PMID 36376273, 2022).
Candidemia (1 paper, 2016). A form of invasive candidiasis where species of CANDIDA are present in the blood. "Although the difference did not quite reach statistical significance, there was a trend toward a decreased percentage of CD4 T cells positive for the IL-7R and decreased MFI in patients with Candidemia compared to controls, p = 0.08 and p = 0.07 respectively." (PMID 26786705, 2016).
cardiac hypertrophy (1 paper, 2025). "Similarly, enriched miR-185-5p was associated with increased IL7R and PWs involved in inflammation, cardiac hypertrophy, and B-cell development." (PMID 40725010, 2025).
cardiac sarcoidosis (1 paper, 2025). Sarcoidosis affecting the tissues of the heart. "While IL7Rα expression has been previously associated with T lymphocytes 12, this study marks the first demonstration of its prominent presence in macrophages within the context of cardiac sarcoidosis." (PMID 40521183, 2025). "The increased expression of CSF1R, IL7R, and IL4R in macrophages, together with the activation of their signaling cascades, suggests a critical role for these receptors in the pathogenesis of cardiac sarcoidosis." (PMID 40521183, 2025).
Chlamydia infection (1 paper, 2024). "We also assessed the effects on innate lymphoid cells (ILC1-3: CD45+ Lin- IL-7Rα+ CD90.2+ T-bet+/-) in the uterus, however, they were absent, or too few present to examine, during Chlamydia infection (Fig. EV1B)." (PMID 38263527, 2024).
clear cell renal carcinoma (1 paper, 2024). A malignant epithelial neoplasm of the kidney characterized by the presence of lipid-containing clear cells within a vascular network. "Compared with the end stage renal failure and the clear cell renal failure, the neutrophil subgroup of the end stage renal failure was dominated by Lgals1_mNeu, while the main cell subgroups of clear cell renal carcinoma were IL-7R + neutrals, Lgals1_mNeu and CD74_Neu." (PMID 38319415, 2024).
demyelinating disease (1 paper, 2017). A broad group of disorders that affect the myelin sheaths that cover the neurons. "This study will not only contribute to elucidating the comprehensive mechanisms governing demyelination, but will also help develop potential IL-7R-based treatments for demyelinating diseases in humans." (PMID 28415697, 2017).
diabetic nephropathy (1 paper, 2025). "The expression levels of IL7R, CD2, GZMA, CD3D and FCER1A significantly differed between diabetic nephropathy and controls." (PMID 41332907, 2025).
endothelial dysfunction (1 paper, 2020). In vascular diseases, endothelial dysfunction is a systemic pathological state of the endothelium (the inner lining of blood vessels) and can be broadly defined as an imbalance between vasodilating and vasoconstricting substances produced by (or acting on) the endothelium. "IL-7R was expressed in vascular endothelial, and both recombinant IL-7 and EGF has shown therapeutic effect on endothelial dysfunction." (PMID 33119592, 2020).
endotoxemia (1 paper, 2011). "Interestingly, whileStat5 is down-regulated, IL-7R is up-regulated inresponse to endotoxemia." (PMID 21437240, 2011).
enteritis (1 paper, 2018). Inflammation of the small intestine. "Moreover, since IL7 promotes naive intestinal T-cell homing and IL7R indicates T cell development, IL7R, up-regulated in the early stages but down-regulated in the middle stages, which indicated the diminishing of enteritis." (PMID 30246797, 2018).
epilepsy (1 paper, 2025). A brain disorder characterized by episodes of abnormally increased neuronal discharge resulting in transient episodes of sensory or motor neurological dysfunction, or psychic dysfunction. "Anti-inflammatory treatments targeting genes, including TNFRSF1A and IL7R, are essential for epilepsy patients exhibiting pronounced inflammatory responses." (PMID 40520613, 2025).
Erythema (1 paper, 2018). Redness of the skin, caused by hyperemia of the capillaries in the lower layers of the skin. "Administration of the site-1/2b anti-IL-7Rα mAbs dramatically prevented memory T cell-mediated skin inflammation after antigen rechallenge as displayed by a marked reduced erythema response and immune cell skin infiltration in all baboons (n = 3 with IgG1 mAb and n = 3 with IgG4 mAb)." (PMID 30367166, 2018). "In contrast, none of the three baboons treated with the site-1 anti-IL-7Rα mAb displayed a reduced erythema response, in spite of a similar pharmacokinetic profile of the antibody and a similar occupancy of the receptors." (PMID 30367166, 2018).
glucocorticoid resistance (1 paper, 2022). "In terms of signaling pathways, RAS/MEK/ERK, IL7R/JAK/STAT, and PI3K/AKT signaling have been found to be associated with glucocorticoid resistance." (PMID 35733807, 2022).
Griscelli syndrome (1 paper, 2023). Griscelli syndrome (GS) is characterized by silvery gray sheen of the hair and hypopigmentation of the skin which can be associated to neurological impairment (type 1), immunodeficiency (type 2) or be isolated (type 3). "Four patients (40%) had a diagnosis of WAS, 5 had a diagnosis of SCID (2 undefined, 2 X-SCID, 1 interleukin-7 receptor (IL7R) defect), and one patient had Griscelli syndrome." (PMID 36930409, 2023).
Headache (1 paper, 2023). Cephalgia, or pain sensed in various parts of the head, not confined to the area of distribution of any nerve. "We selected the genes CCL4 and IL7R, which are regulatory T-cell-associated markers, for local AE and headache, respectively." (PMID 38022684, 2023). "The genes CCL4 and IL7R were associated with local AE and headache, respectively." (PMID 38022684, 2023).
heart failure (1 paper, 2025). Inability of the heart to pump blood at an adequate rate to meet tissue metabolic requirements. "Taken together, the high expression and activation of IL7Rα, PI3K/Akt, and Jak2/STAT5, we infer that the IL7 signaling pathway is activated in macrophages within the granuloma of patients with heart failure." (PMID 40521183, 2025).
Huntington disease (1 paper, 2022). Huntington disease (HD) is a rare neurodegenerative disorder of the central nervous system characterized by unwanted choreatic movements, behavioral and psychiatric disturbances and dementia. "However, at 14 weeks of age in males, FMT increased IL-17E levels (P = 0.04), and IL-7R was found to be increased in Huntington’s disease mice (P = 0.01)." (PMID 36035436, 2022).
insomnia (1 paper, 2025). A sleep disorder characterized by difficulty in falling asleep and/or remaining asleep. "We conducted WB experiments to detect the differences in protein expression levels of BCL2, SOCS3, and IL7R indicators in hippocampal neurons of normal control and insomnia model groups." (PMID 39833072, 2025). "In this study, BCL2, SOCS3, and IL7R were all under-expressed in the hippocampal neurons of the insomnia model compared with the control group, suggesting a decreased antiapoptotic capacity." (PMID 39833072, 2025). "Overall, our results indicate that BCL2, SOCS3, and IL7R may play important regulatory roles in the development of insomnia." (PMID 39833072, 2025). "In conclusion, our study verified that apoptosis is closely related to the development of insomnia, and BCL2, SOCS3, and IL7R have the potential to be therapeutic targets for insomnia." (PMID 39833072, 2025). "A total of 190 differentially expressed apoptosis-related genes were identified in insomnia, and BCL2, SOCS3, and IL7R were identified as important hub genes." (PMID 39833072, 2025). "Through bioinformatic data analysis, we clarified that apoptosis signaling pathway plays an important role in the development of insomnia, and that the 3 hub genes, BCL2, SOCS3, and IL7R, are most likely involved in the development of insomnia." (PMID 39833072, 2025). "Although BCL2 has been studied in the context of sleep deprivation, SOCS3 and IL7R have not yet been explored in insomnia." (PMID 39833072, 2025). "Importantly, the decrease in BCL2, SOCS3, and IL7R indexes indicated that the antiapoptotic capacity of hippocampal neurons in the insomnia model group was weakened, and thus it is highly likely that BCL2, SOCS3, and IL7R are important targets in the development of insomnia." (PMID 39833072, 2025).
lung squamous cell carcinoma (1 paper, 2022). "In addition, IL7R is also significantly correlated with PD-1 expression, which may be a predictive marker for the PD-1 inhibitor response in patients with PD-L1-negative lung squamous cell carcinoma." (PMID 36358600, 2022).